TRIM16L (tripartite motif containing 16 like (pseudogene))
Synonyms: TRIM70
Gene: Transcribed unprocessed pseudogene on chromosome 17 (18,722,237 to 18,735,460, forward strand). Ensembl gene ENSG00000108448.
Subcellular location: Cytoplasm
Diseases named in the same sentence as TRIM16L in open-access papers:
TRIM16L is named in the same sentence as 5 diseases in open-access papers, as found by Europe PMC text mining. Sharing a sentence is not in itself a finding about the gene and the disease. The quoted sentences say what the papers report.
head and neck cancer (1 paper, 2019). A primary or metastatic malignant neoplasm affecting the head and neck. "Notably, our recent study on TCGA- head and neck cancer also identified the overexpression of TRIM16L and UCHL1 in KEAP1-NRF2-CUL3 axis altered patients." (PMID 31839815, 2019).
tumor (3 papers, 2020 to 2023). "RASSF6 and TRIM16L have been identified as tumor-suppressor proteins." (PMID 37891913, 2023).
cancer (2 papers, 2018 to 2020). A tumor composed of atypical neoplastic, often pleomorphic cells that invade other tissues. "The exact functions of the other two putative KEAP1-NRF2-CUL3axis-regulated genes, RAB6B and TRIM16L, are unknown in cancer cells and therefore are under investigation in our lab." (PMID 29306329, 2018).
TRIM16L also shares sentences with these, for which no sentence is quoted: colon cancer (1 paper); virus infection (1).